TMEM238 (transmembrane protein 238)
Tractability: Antibody: UniProt predicts a signal peptide or a membrane-spanning region.
Gene: Protein-coding gene on chromosome 19 (55,379,244 to 55,384,292, reverse strand). Ensembl gene ENSG00000233493.
Subcellular location: Membrane
Gene Ontology:
Cellular component: membrane
Genetic constraint (gnomAD): Missense variants: 9 observed, 7.9 expected, observed/expected ratio (o/e) 1.14, 90% interval 0.68 to 1.81. Synonymous variants: 6 observed, 5.22 expected, observed/expected ratio (o/e) 1.15, 90% interval 0.61 to 1.86.
Homologues: Orthologues: macaque TMEM238 (97% identical), pig TMEM238 (93% identical), dog TMEM238 (91% identical), mouse Tmem238 (85% identical), rat Tmem238 (85% identical), guinea pig TMEM238 (79% identical), tropical clawed frog tmem238 (39% identical), zebrafish tmem238a (28% identical).
Diseases named in the same sentence as TMEM238 in open-access papers:
TMEM238 is named in the same sentence as 2 diseases in open-access papers, as found by Europe PMC text mining. Sharing a sentence is not in itself a finding about the gene and the disease.
TMEM238 shares sentences with these, for which no sentence is quoted: cancer (1 paper); prostate carcinoma (1).